SUSD6 (sushi domain containing 6)
Description:
May play a role in growth-suppressive activity and cell death. May be involved in the production of chemokine molecules in umbilical vein endothelial cells (HUVECs) cultured in THP1 monocyte LPS-induced medium. Plays a role in preventing tumor onset (By similarity).
Synonyms: DRAGO; KIAA0247
Tractability: Antibody: UniProt predicts a signal peptide or a membrane-spanning region; the Human Protein Atlas places it where antibodies can reach.
Gene: Protein-coding gene on chromosome 14 (69,611,591 to 69,715,144, forward strand). Ensembl gene ENSG00000100647.
Subcellular location: Membrane
Subcellular location (Human Protein Atlas): Plasma membrane; Cytosol
Gene Ontology:
Molecular function: protein binding
Biological process: DNA damage response
Cellular component: membrane
Genetic constraint (gnomAD): Loss-of-function variants: 16 observed, 29.86 expected, observed/expected ratio (o/e) 0.54, 90% interval 0.36 to 0.81. The upper end of that interval is the gene's LOEUF score, 0.81, which puts it in group 3 of 6, group 1 being the genes least tolerant of losing a copy. Missense variants: 341 observed, 403.81 expected, observed/expected ratio (o/e) 0.84, 90% interval 0.77 to 0.92. Synonymous variants: 147 observed, 169.01 expected, observed/expected ratio (o/e) 0.87, 90% interval 0.76 to 1.
Homologues: Orthologues: chimpanzee SUSD6 (99% identical), macaque SUSD6 (98% identical), pig SUSD6 (93% identical), rabbit SUSD6 (92% identical), guinea pig SUSD6 (90% identical), rat Susd6 (90% identical), mouse Susd6 (89% identical), dog SUSD6 (84% identical), tropical clawed frog susd6 (63% identical), zebrafish susd6 (53% identical). Paralogues in human: CSMD1 (20% identical), CSMD3 (20% identical), CSMD2 (19% identical), SVEP1 (18% identical), CFH (17% identical), SEZ6L2 (16% identical), SUSD4 (16% identical), CR1 (15% identical), SELE (15% identical), CR2 (14% identical), C6 (14% identical), CFHR5 (14% identical), and 27 more.
Diseases named in the same sentence as SUSD6 in open-access papers:
SUSD6 is named in the same sentence as 13 diseases in open-access papers, as found by Europe PMC text mining. Sharing a sentence is not in itself a finding about the gene and the disease. The quoted sentences say what the papers report.
acute myeloid leukemia (1 paper, 2024). Acute myeloid leukemia (AML) is a group of neoplasms arising from precursor cells committed to the myeloid cell-line differentiation. "In acute myeloid leukemia (AML), the sushi domain containing 6 (SUSD6) interacts with transmembrane protein 127 (TMEM127) and MHC-I, recruiting the E3 ubiquitin ligase WWP2." (PMID 39223632, 2024).
melanoma (1 paper, 2019). A malignant, usually aggressive tumor composed of atypical, neoplastic melanocytes. "A melanoma-specific similar mechanism of aberrant splicing seems to also operate for the SUSD6 gene (asterisks)." (PMID 30795533, 2019).
tumor (7 papers, 2008 to 2025). "Association mapping of the chromosome 12 locus localized its effect to a region encompassing ∼18 genes, including DRAGO/Susd6, a DNA damage-responsive tumor suppressor and Rgs6, a regulator of G-protein signaling." (PMID 40326784, 2025). "In the presence of SUSD6 and TMEM127, WWP2 mediates MHC-I ubiquitination as well as lysosomal degradation, thereby reducing MHC-I surface expression, loss of SUSD6 enhances MHC-I surface expression, which can promote the function of CD8+ T cells, thereby enhancing tumor immune surveillance." (PMID 38082437, 2023). "TMEM127 interacts with an endogenous transmembrane protein, SUSD6, and WWP2 to mediate the reduction of MHCI in tumour cells." (PMID 41135677, 2025). "Given its role as a tumor suppressor, DRAGO/Susd6 on chromosome 12 is a strong candidate." (PMID 40326784, 2025).
SUSD6 also shares sentences with these, for which no sentence is quoted: cancer (2 papers); colorectal cancer (2); glioma (2); cholangiocarcinoma (1); colorectal tumor (1); diabetic kidney disease (1); metabolic disease (1); neurodegenerative disease (1); ovarian tumor (1); Sinus bradycardia (1).